ANTXR1 (ANTXR cell adhesion molecule 1)
Diseases named in the same sentence as ANTXR1 in open-access papers (continued):
Sharing a sentence is not in itself a finding about the gene and the disease.
tumor (continued). "In tumors, nutrients stress and ischemia induce ANTXR1, which promotes angiogenesis and tumor growth." (PMID 41039173, 2025). "We selected CXCR7, angiopoietin 2, and ANTXR1 (also known as tumor endothelial marker 8, TEM 8), as putative markers of TEC." (PMID 40348600, 2025). "We also investigated the pathways that are enriched in tumors downstream of the ANTXR1 gene to complement the effect of this gene in the tumor metabolism." (PMID 39917181, 2024). "The SVV oncolytic activity is mediated by the viral cellular receptor anthrax toxin receptor 1 (ANTXR1), also known as tumor endothelial marker 8 (TEM8)." (PMID 37174006, 2023). "Antxr1 is important for promoting tumour angiogenesis, and it has been reported that Antxr1 blockade inhibits pathologic angiogenesis and that overexpression of Antxr1 stimulates the migration of endothelial cells." (PMID 37833999, 2023). "ANTXR Cell Adhesion Molecule 1 (ANTXR1) is a type I transmembrane protein and a tumor-specific endothelial marker." (PMID 36833280, 2023). "The role of ANTXR1 in tumor development has been demonstrated in previous studies, but no studies have examined its effects on hematopoiesis and erythrocyte differentiation." (PMID 36065334, 2022). "This test detects TEM8/ANTXR1 as well as seven additional genes to accurately predict if the patient’s tumor is permissive to SVV infection." (PMID 36090051, 2022). "The specific association between upregulated TEM8/ANTXR1, vasculogenic mimicry, and cancer stem cells, suggests the presence of a hypoxic tumor microenvironment with disordered angiogenesis, which promotes the survival and spread of cancer cells." (PMID 36090051, 2022). "Endotrophin (ETP), a cleavage product of the COL6A3 chain, increases tumor stem cell-like cells though activating the anthrax toxin receptor 1 (ANTXR1)." (PMID 36167487, 2022). "All of these characteristics suggest a type of hypoxia-driven highly vascular tumor microenvironment similar to the environment that in other tumor types are enriched for TEM8/ANTXR1." (PMID 36090051, 2022). "ANTXR1 was initially found in tumor vascular endothelial cells and promote tumor vascular endothelial formation." (PMID 36065334, 2022). "In preclinical murine models, an antibody-drug conjugate targeting TEM8/ANTXR1 led to tumor regression and improved survival." (PMID 36090051, 2022). "TEM8/ANTXR1 is an integrin-like, transmembrane glycoprotein upregulated in a variety of cancer types, tumor associated stromal cells, and tumor-associated blood vessels." (PMID 36090051, 2022). "ANTXR1, also known as tumor endothelial marker 8 (TEM8), is a highly conserved transmembrane glycoprotein overexpressed on tumor vasculature." (PMID 35480887, 2022). "All clinical studies were done prior to the discovery that TEM8/ANTXR1 is the receptor for SVV-001 on tumor and stromal cells and a potentially valuable biomarker for patients who would most benefit from therapy with SVV-001." (PMID 36090051, 2022). "Antibodies blocking the TEM8/ANTXR1 extracellular domain inhibit tumor related angiogenesis and tumor growth." (PMID 36090051, 2022). "Anthrax toxin receptor 1 (ANTXR1) was initially discovered as a tumor endothelial marker, also known as tumor endothelial marker 8 (TEM8)." (PMID 35071028, 2021). "Another target known as TEM8 (tumor endothelial marker), or ANTXR1, is an integrin-like protein known to be highly expressed in endothelium during endothelial cell development in mice but is minimally detectable in adult mice." (PMID 33670942, 2021). "We further revealed the differential landscape of somatic tumor mutation burden (TMB) between the two groups and observed that patients with high ANTXR1 expression suffered from a lower TMB, potentially leading to less sensitivity to checkpoint therapy." (PMID 33385012, 2020). "ANTXR1, also known as tumor endothelial marker 8 (TEM8), is widely considered a potential target for cancer therapy because of its effect on tumor angiogenesis." (PMID 32695142, 2020).
tumor (continued). "The results of the correlation analyses showed that CD8+ T cells, CD4+ T cells, macrophages, neutrophils, and dendritic cells were positively correlated with the expression of ANTXR1, while they were negatively correlated with tumor purity." (PMID 33385012, 2020). "Anthrax toxin receptor 1 (ANTXR1), otherwise known as tumor endothelial marker 8 (TEM8), is a highly conserved transmembrane glycoprotein overexpressed on tumor vasculature." (PMID 33385012, 2020). "Since we found that ANTXR1 was aberrantly expressed in GC and correlated with tumor progression, its prognostic value was further investigated." (PMID 33385012, 2020). "ANTXR1 has been reported to participate in tumor progression in numerous kinds of carcinomas, and its overexpression in tumor cells makes it a promising prognostic biomarker and therapeutic target accordingly." (PMID 33385012, 2020). "Anthrax toxin receptor 1 (Antxr1)/tumor endothelial marker 8 (Tem8) was discovered in the screening of proteins expressed in tumor endothelium at an increased level and identified as a receptor for protective antigen (PA) of anthrax toxin." (PMID 32244499, 2020). "This study strongly suggested that in addition to being expressed on the tumor vasculature, ANTXR1 is also expressed on tumor cells allowing for LeTx-mediated elimination of these cells." (PMID 31191663, 2019). "While ANTXR1/TEM8 overexpression has been observed in different tumor entities, its expression and putative role in PDAC have not been rigorously examined to date." (PMID 31191663, 2019). "ANTXR1 is a single-pass cell-surface glycoprotein originally identified in the tumor-infiltrating vasculature." (PMID 27894102, 2016). "Previous studies have demonstrated that targeting Antxr1 reduces tumor vascular density and is an effective strategy to slow tumor growth and prolong survival." (PMID 26785120, 2016). "TEM8 or ANTXR1 is an anthrax toxin receptor which has been identified as a tumour endothelial marker." (PMID 26620208, 2016). "Anthrax toxin receptor 1/tumor endothelial marker 8 (Antxr1 or TEM8) is up-regulated in tumor vasculature and serves as a receptor for anthrax toxin, but its physiologic function is unclear." (PMID 26785120, 2016). "A recent follow-up study using these Antxr1 KO mice bred to an immunodeficient background revealed slower growth of multiple human tumor xenografts that was due in part to reduced tumor vasculature." (PMID 23389402, 2013). "Pathological angiogenesis in the Antxr1 KO mice also appeared to be unaltered, when analyzed by performing syngeneic tumor implant studies." (PMID 23389402, 2013). "While human ANTXR1 was originally reported to be a tumor endothelial marker, the Antxr1 KO mouse phenotype suggested more widespread expression of Antxr1, as ECM homeostasis defects are seen in tissues and cell types beyond tumor endothelium." (PMID 23389402, 2013). "In as much as ANTXR1/TEM8 shows enhanced expression in at least some tumor endothelial cells, the gene does appear to be a player in tumor vasculature development." (PMID 22912819, 2012). "Tumor Endothelial Marker 8/Anthrax Toxin Receptor 1 (TEM8/ANTXR1) expression is induced in the vascular compartment of multiple tumors and therefore, is a candidate molecule to target tumor therapies." (PMID 21829615, 2011). "For example, tumor C3H BF had Wnt1 as a CIS in addition to Tcf7l2, while insertion of MMTV at Antxr1 and Wnt3 in tumor Balb 5 resulted in the expression of both CISs." (PMID 22087314, 2011). "The gene list they identified shares similarities to gene expressed in our whole tumour sample (ANTXR1, COL12A1, COL5A2, CTHRC1, POSTN)." (PMID 19401702, 2009). "The advantages of targeting TEM8/ANTXR1 include its overexpression in tumor-associated endothelial cells and certain tumor cells, which can potentially enhance the specificity of treatments towards tumor tissues." (PMID 40849468, 2025).
tumor (continued). "After understanding the impact of ANTXR1 expression in tumors and its impact on tumor prognosis, we wanted to further investigate the possible mechanisms and/or pathways that were impacted by the expression of ANTXR1 that might lead to poor prognosis." (PMID 39917181, 2024). "DNA vaccines against Antxr1 can inhibit tumour angiogenesis." (PMID 37833999, 2023). "It is important to note that recent studies have found that SVA can specifically target tumor cells that express ANTXR1 without causing any off-target effects on normal cells with highly expressed ANTXR2." (PMID 35371972, 2022). "ANTXR1 is a receptor for anthrax toxin and is highly expressed in tumor endothelial cells." (PMID 36313435, 2022). "In addition antibodies against TEM8/ANTXR1 have demonstrated anti-tumor activity and had synergistic effects with other anti-cancer agents." (PMID 36090051, 2022). "Other molecules that have a role in tumor growth and progressions, such as anthrax toxin receptor 1 (ANTXR1), lamin receptor, intracellular adhesion molecule-1 (ICAM-1), and decay-accelerating factor (DAF), also can serve as a receptor for SVV-001, Sindbis virus, and coxsackievirus, respectively." (PMID 34771615, 2021). "Moreover, an antibody against Antxr1 inhibits tumor-induced angiogenesis, suggesting that Antxr1 expression in the endothelium is required for the proliferation of endothelial cells and angiogenesis in cancer growth." (PMID 32244499, 2020). "Antxr1 in the tumor endothelium interacts with the C-terminal C5 domain of collagen α3(VI)." (PMID 32244499, 2020). "Antxr1/Tem8 is highly expressed in tumor endothelial cells and is a receptor for anthrax toxin." (PMID 32244499, 2020). "Collectively, these findings indicated that ANTXR1 may participate in regulating the tumor stromal environment and promotes tumor metastasis." (PMID 33385012, 2020). "Likewise, adapting PA and LF components to increase their biological activity and minimize toxicity, synthesizing mutant PA moieties with more potent antiangiogenic and tumor growth properties, and developing anti-ANTXR1 antibodies have also been explored." (PMID 31191663, 2019). "Thus, this study validates ANTXR1 as a new PaCSC marker and we propose its use in identifying CSCs in this tumor type and its exploitation in the development of CSC-targeted therapies for PDAC." (PMID 31191663, 2019). "Tumor endothelial marker 8 (TEM8), a type I membrane protein, was originally identified by virtue of its elevated expression during tumor angiogenesis, and subsequently discovered to be a receptor for anthrax toxin, hence its official name, anthrax toxin receptor 1 (ANTXR1)." (PMID 30241478, 2018). "ANTXR1, a single-pass transmembrane glycoprotein, shares common features with the immunoglobulin superfamily proteins which include many picornavirus receptors, and is also a tumor endothelial marker in humans." (PMID 29867849, 2018). "ANTXR1 is frequently expressed on the surface of tumor cells compared with normal human cells." (PMID 29867849, 2018). "This approach was selected since Antxr1 is highly expressed in tumor endothelial cells." (PMID 23389402, 2013). "As Antxr1 KO mice develop normally and thrive but fail to support strong tumor growth, it has been hypothesized that a key function of ANXTR1 may be to serve in stress-mediated responses." (PMID 23389402, 2013). "Among the upregulated genes, we identified several oncogenes (Ets2, Fyn, Fos, Rab30 and Src), various tumor markers (Cyp1b1, Gpa33, Cd47, Fam129a, st7l, chka, Lgalsbp, Antxr1 and Ly6a) and other genes related to tumor promotion (Cxcl10, Trim25, Grn, Foxc2, Bmp7 and Irs1)." (PMID 23936067, 2013). "Thus, ANTXR1 is highly expressed in tumor endothelium, functions in tumor growth, and appears to regulate ECM homeostasis in several organs of the mouse." (PMID 23389402, 2013). "TEM8/ANTXR1 is unique in its association with tumor vessels but not normal blood vessels." (PMID 36090051, 2022).
tumor (continued). "Inhibition of ANTXR1 could repress the angiogenesis of tumor tissues." (PMID 35480887, 2022). "However, this tumor had integrations at both Tcf7l2 and Antxr1 which could potentially result in enhanced signaling by over-expression of 2 genes in the same WNT pathway." (PMID 22087314, 2011). "Thus, in the case of MMTV, insertion of the virus at both the Wnt and Antxr1 loci in a single tumor could potentiate growth of the transformed cells." (PMID 22087314, 2011). "Tumor growth and metastasis were inhibited by antibodies that blocked TEM8/ANTXR1 or TEM8/ANTRX1 knockdown genetically." (PMID 39755633, 2025). "The anthrax toxin protective antigen (PA) also targets receptors that can be upregulated in tumors, namely tumor endothelial marker 8 (TEM8, ANTXR1) that is involved in tumor angiogenesis." (PMID 34067057, 2021). "CAFs-derived lactate is imported into tumor cells via MCT1 and induces lactylation of anthrax toxin receptor 1 (ANTXR1) at K453, which stabilizes ANTXR1 and activates the RhoC/ROCK1/SMAD5 pathway, thereby enhancing cancer stemness and driving oxaliplatin resistance." (PMID 41152975, 2025). "Future studies need to investigate the role of ANTXR1 expression in other pathways like EGFR, the complement and coagulation cascades, as well as metastatic pathways including the potential role of TEM8 in the EMT process (with uPA and transgelin), and its importance in tumor biology." (PMID 39917181, 2024). "Some studies have demonstrated that the endothelium of several neoplasms often overexpresses an integrin-like protein called tumor endothelial marker 8 (TEM8), also known as ANTXR1, and is usually expressed during endothelial cell development but rarely in adults." (PMID 36900394, 2023). "It is widely accepted that the stroma of tumor microenvironment (TME) is correlated with the resistance of chemotherapy of cancer; thereby, we evaluated whether ANTXR1 is a predictor for GC patients' response to chemotherapy." (PMID 33385012, 2020). "This further demonstrated that ANTXR1 might promote TME remodeling, especially affecting the elements of tumor stroma, which can lead to chemoresistance." (PMID 33385012, 2020). "To assess the expression level of ANTXR1 in patients with GC, we compared the expression level of ANTXR1 in non-paired tumor and adjacent tissues and paired samples, and the MET was considered as positive control while ACTB was considered as negative control." (PMID 33385012, 2020). "While this highlights an important role for ANTXR1 in breast CSCs, the expression of ANTXR1 on CSCs from other tumor entities, such as PDAC, has not been explored to date." (PMID 31191663, 2019). "The researchers confirmed that Antxr1 transcripts and protein were not being expressed in the Antxr1 KO mice by implanting tumors in wild-type (WT) and KO mice and then isolating tumor endothelial cells for RT-PCR and Western blot analysis." (PMID 23389402, 2013). "While there was significant growth inhibition of B16 melanoma tumors implanted in Antxr1 KO mice, the growth delay did not correlate with significant differences in tumor vessel density or pericyte coverage." (PMID 23389402, 2013). "Additionally, we observed that mATC cells overexpressed receptors such as FGFR1, EPHB2, PDGFRA, NOTCH3, ANTXR1, and NRP1, which could receive signals from CAFs and thereby promote tumor cell proliferation and aggressiveness." (PMID 37053016, 2023). "Thus, the mechanism by which Antxr1 contributes to tumor growth in this particular study was not delineated but clearly involved a stromal component of the tumor microenvironment." (PMID 23389402, 2013).
cancer (53 papers, 2011 to 2025). A tumor composed of atypical neoplastic, often pleomorphic cells that invade other tissues. "Global ANTXR1 disruption protects against cancer and causes progressive collagen accumulation in multiple organs, suggesting a role in regulating collagen deposition." (PMID 41039173, 2025). "The downstream activated pathways found in solid cancers with high expression of ANTXR1 confirmed what has been found in previous studies in other types of cancer., i.e., to be linked with cancer aggressiveness, invasion and metastasis." (PMID 39917181, 2024). "ANTXR1 expression is known to correlate with cancer-associated fibroblasts and TAM, which allows for phenotypic differentiation into M1 or M2 macrophages, as well as the secretion of immunosuppressive factors." (PMID 37998358, 2023). "Taken as a whole, these data highlight the relevance of the decrease in the ANTXR1+ ECM-myCAF cluster content after chemotherapy in various cancer types by using several complementary approaches." (PMID 38346978, 2024). "That there is more ANTXR1 expressed with a greater amount of stroma cells is congruent with the fact that ANTXR1 expression has been found in some stromal cells including cancer stem cells." (PMID 39917181, 2024). "We analyzed eleven different types of cancer for differences of immune score in varying rates of expression of ANTXR1 in tumors (same types of cancer as the stromal score)." (PMID 39917181, 2024). "Six out of the eleven types of cancer analyzed showed a statistically significant difference of the stromal score when comparing high or low expression levels of ANTXR1 in each group." (PMID 39917181, 2024). "More clinical data analyzed within each cancer type can further clarify the impact of ANTXR1 expression in these cases." (PMID 39917181, 2024). "Although we described a bioinformatic study analyzing clinical data from patients with different types of cancers, further investigations must address not only the ANTXR1 expression at the RNA, but at the protein level (TEM8)." (PMID 39917181, 2024). "Other studies have also shown a connection between TEM8/ANTXR1 and endothelial cell response to Wnt signaling in cancer, with upregulation of TEM8/ANTXR1 associated with activation of downstream targets of Wnt pathways." (PMID 36090051, 2022). "Previous studies have reported that ANTXR1 can facilitate the activation of the canonical Wnt signaling pathway in a variety of cancers." (PMID 35942209, 2022). "Additional research is needed to fully clarify the role of TEM8/ANTXR1 in activation of Wnt/β-catenin signaling pathways and the relationship between this pathway and outcomes in different cancer types." (PMID 36090051, 2022). "Namely, CLEC14A, CD93, endoglin, and ANTXR1 (alias TEM8) have shown to be overexpressed in several cancers." (PMID 34770976, 2021). "ANTXR1 can facilitate the entrance of anthrax toxin into cells and has been demonstrated to be overexpressed in several cancer types including gastric, breast, colon, and pancreatic tumors." (PMID 33385012, 2020). "Recent studies validated that anthrax toxin receptor 1 (ANTXR1) is aberrantly expressed in several cancers and holds promise as a new therapeutic target for cancer." (PMID 33385012, 2020). "Tumor endothelial marker 8 (TEM8, also known as ANTXR1) was found to be highly expressed in cancer-associated fibroblasts and other stromal cells in a variety of cancers." (PMID 31101063, 2019). "To test PASTMUS strategy in mapping functional elements of proteins, we selected three genes (ANTXR1, CSPG4, and HBEGF) encoding bacterial toxin receptors and three genes (HPRT1, PLK1, and PSMB5) encoding cancer drug targets." (PMID 31842968, 2019). "Genes that are implicated in angiogenesis were also identified; both VCAN and ANTXR1 promote angiogenesis for cancer progression." (PMID 23372686, 2013).